FSCN1 (fascin actin-bundling protein 1)
Diseases named in the same sentence as FSCN1 in open-access papers (continued):
Sharing a sentence is not in itself a finding about the gene and the disease.
esophageal cancer (17 papers, 2012 to 2024). A primary or metastatic malignant neoplasm involving the esophagus. "LINC01711 is markedly expressed in esophageal cancer and has been linked to substandard prognosis by promoting tumor cells proliferation, migration, and invasion properties through FSCN1 upregulation and miR-326 downregulation." (PMID 38071230, 2023). "It was found that the phosphorylation level of the FSCN1 protein is correlated with the occurrence and development of esophageal cancer." (PMID 35178306, 2022). "In general, exosomal LINC01711 promoted the proliferation, migration, and invasion of esophageal cancer cells by up-regulating FSCN1 and down-regulating miR-326, thus improved the occurrence and development of ESCC." (PMID 34370713, 2021). "LncRNA LINC01711 promoted the proliferation, migration, and invasion of esophageal cancer cells by up-regulating FSCN1 and down-regulating miR-326, and inhibiting apoptosis, thus promoted the occurrence and development of esophageal cancer." (PMID 34370713, 2021). "FSCN1 is involved in the pathogenesis and metastasis of esophageal carcinoma; high FSCN1 expression increases gradually from the normal to the invasive form and correlates with cell proliferation, lymph node invasion, metastasis, and high tumor stage." (PMID 34830909, 2021). "Knockdown of lncRNA PVT1 reduces cell migration and invasion and increases cell apoptosis via miR-145-mediated inhibition of FSCN1 in esophageal carcinoma cell." (PMID 33614632, 2020). "In addition, FSCN1, as an independent poor prognostic marker for aggressiveness, has been evaluated in multiple patient populations of some cancers (e.g., breast, colon, and esophageal cancer)." (PMID 33614909, 2021). "In conclusion, since miR-143 and miR-145 could regulate oncogenic FSCN1 and take part in the modulation of metastases, the result suggested the combination variable of miR-143 and miR-145 as a potential biomarker for earlier diagnosis and prognosis of esophageal cancer." (PMID 22457808, 2012). "In esophageal cancer, the lncRNA–TTN–AS1 enhanced FSCN1 expression through miR-133b sponges." (PMID 38077434, 2023). "FSCN1 can regulate the expression of CTGF and CYR61 by downregulating the expression of the activating factor THBS1 in TGF-β pathway, thus affecting the proliferation and invasion of esophageal cancer cells." (PMID 35178306, 2022). "It was shown to be downregulated and might function as a tumor suppressor by targeting Myc, FSCN1 in gastric cancer, ZEB1 in oral squamous cell carcinoma, CRKL in hepatocellular carcinoma, TLN1 in nasopharyngeal carcinoma, AKT1 in melanoma, or BCL2 and SP1 in esophageal carcinomas." (PMID 33414893, 2020).
gastric cancer (16 papers, 2012 to 2022). A primary or metastatic malignant neoplasm involving the stomach. "Our bioinformatics data indicated that FSCN1 mRNA expression was negatively associated with overall and progression-free survival rates of the patient with gastric cancer, even stratified by clinicopathological features." (PMID 29285273, 2017). "Although several reports have implicated the regulation of FSCN1 by miRs in many carcinomas, to the best of our knowledge, no report has suggested that FSCN1 is a direct target of miR-145 in gastric cancer." (PMID 26010149, 2015). "Likewise, in EBV-associated gastric cancer, upregulated Smad4/FSCN1 expression significantly correlated with larger tumor size, higher histological grade, lymph node involvement, vascular invasion, and poor clinical outcome." (PMID 34830909, 2021). "Moreover, FSCN1 expression is linked with a high risk of distant and lymph node metastasis in colorectal and gastric carcinomas." (PMID 34830909, 2021). "In gastric cancer, one study reported that Fas signaling induces FSCN1 expression via the STAT3 pathway; another study demonstrated that galectin-3 regulates the GSK-3β/β-catenin/TCF-4 signaling pathway, thus triggering FSCN1 expression." (PMID 34830909, 2021). "In gastric cancer, the induction of FSCN1 expression by TGF-β is partially dependent on Smad3 linker phosphorylation." (PMID 33614909, 2021). "On the other hand, gastric carcinoma studies using TMA and IHC reported FSCN1 overexpression at both mRNA and protein levels; high FSCN1 expression is associated with tumor size, poorly differentiated tumors, invasion, metastasis, TNM stage, and poor survival." (PMID 34830909, 2021). "FSCN1 was reported to bind miR-326 in gastric cancer, and our study supports the interaction between these two genes." (PMID 32493389, 2020). "In nasopharyngeal carcinoma and gastric cancer, however, it was identified as an antioncogene and was shown to target FSCN1 and RegIV." (PMID 29850625, 2018). "According to bioinformatics database, FSCN1 mRNA expression was higher in gastric cancer than normal tissues (p<0.05)." (PMID 29285273, 2017). "Then, we used Cho's, DErrico's, Cui's and Wang's datasets to perform bioinformatics analysis and found that FSCN1 expression was higher in gastric cancer than normal tissues, even stratified into intestinal-, diffuse- and mixed-type carcinoma (p<0.05)." (PMID 29285273, 2017). "Knocking down the expression of FSCN1 led to the suppression of migration and invasion in gastric cancer cells, and re-expressing FSCN1 in miR-145-overexpressing cells reversed their migration and invasion defects." (PMID 26010149, 2015). "The present study shed new light on the correlation between miR-145 and FSCN1 in infiltrative gastric cancer." (PMID 26010149, 2015). "We tested the expression of miR-145 and FSCN1 mRNA in gastric cancer compared to the adjacent normal gastric mucosa by real-time PCR." (PMID 26010149, 2015). "Collectively, these studies provided compelling evidence that FSCN1 is a direct target of miR-145 in gastric cancer cells." (PMID 26010149, 2015). "In contrast, the overall mRNA/protein levels of FSCN1 were higher in the infiltrative gastric cancer." (PMID 26010149, 2015). "Meanwhile, a stronger inverse correlation was also detected between miR-145 and FSCN1 expression levels in infiltrative gastric cancer." (PMID 26010149, 2015). "Functionally, we demonstrated that miR-145 suppresses cell migration and invasion in gastric cancer primarily by directly targeting FSCN1." (PMID 26010149, 2015). "In this study, we confirmed that miR-145 represses FSCN1 expression and directly targets the 3’ UTR of FSCN1 in gastric cancer cells." (PMID 26010149, 2015). "In summary, the present study identified that miR-145 is primarily down-regulated in infiltrative gastric cancer and that miR-145 expression and FSCN1 expression have a strong inverse correlation in infiltrative gastric cancer." (PMID 26010149, 2015).
gastric cancer (continued). "Secondly, an inverse correlation between miR-145 and FSCN1 was found in the paired samples from gastric cancer patients." (PMID 26010149, 2015). "To determine if miR-145 regulates the expression of FSCN1 in gastric cancer cells, we first up-regulated the level of miR-145 in gastric cancer MGC-803 cells using a lentivirus-based vector." (PMID 26010149, 2015). "miR-145 was remarkably down-regulated in infiltrative gastric cancer compared to expanding gastric cancer, while the expression of FSCN1 mRNA was remarkably up-regulated." (PMID 26010149, 2015). "As infiltrative gastric cancer is more invasive than expanding gastric cancer, these results suggest that miR-145 and FSCN1 both play crucial roles in gastric cancer invasion." (PMID 26010149, 2015). "Moreover, data obtained from 80 samples of gastric cancer patients indicated that FSCN1 promotes EMT in gastric cancer." (PMID 35711849, 2022). "However, in breast or gastric cancer tissues, the average frequency of FSCN1 upregulation is 27% and 33%, respectively." (PMID 33614909, 2021). "Consequently, the expression of miR-145 and its putative target FSCN1 had a strong inverse relation in human infiltrative type gastric cancer, thereby suggesting that the essential roles of miR-145 and FSCN1 are in gastric cancer invasion." (PMID 26010149, 2015). "Moreover, we provided evidence that miR-145 suppressed cell migration and invasion in gastric cancer primarily by directly targeting FSCN1, which highlighted the role of miR-145 and FSCN1 in the regulation of gastric cancer malignant phenotypes." (PMID 26010149, 2015). "Thus, we concluded that miR-145 regulates cell migration and invasion in gastric cancer primarily by directly targeting FSCN1." (PMID 26010149, 2015). "Additionally, correlation analyses revealed strong inverse correlations between miR-145 and FSCN1 expression levels in infiltrative gastric cancer." (PMID 26010149, 2015). "Furthermore, we demonstrated that miR-145 directly targets FSCN1 and suppresses cell migration and invasion in gastric cancer." (PMID 26010149, 2015). "Moreover, a series of studies have indicated that enforced FSCN1 expression increases the proliferation and invasion of ovarian and gastric cancer cells." (PMID 26010149, 2015). "Therefore, FSCN1 is an important downstream target of miR-145 in regulating gastric cancer invasion." (PMID 26010149, 2015). "First, we investigated whether the correlation of miR-145 and FSCN1 could be clinically relevant by measuring the expression of miR-145 and FSCN1 mRNA/protein levels in normal/tumor paired samples from 80 patients with gastric cancer." (PMID 26010149, 2015). "Evidence shows that FSCN1 is involved in the EMT process in a number of cancer types, including squamous cell carcinoma, cholangiocarcinoma, gastric cancer, and ovarian cancer." (PMID 33614909, 2021). "Gastric cancer MGC-803 and SGC-7901 cells were stably transfected with two different FSCN1 shRNAs to inhibit FSCN1 to better understand the potential role of FSCN1 in miR-145–mediated tumor migration and invasion." (PMID 26010149, 2015).
lung cancer (16 papers, 2016 to 2026). A malignant neoplasm involving the lung. "Our data provide global insights into the regulatory mechanisms associated with the roles of FSCN1 and its target genes in lung cancer." (PMID 38077434, 2023). "Our data provide global insights into the regulatory mechanisms mediated by FSCN1 and its target genes in lung cancer." (PMID 38077434, 2023). "CircRNA SATB2 participates in lung cancer progression by regulating miR-326/fascin homolog 1 and the actin-bundling protein 1 (FSCN1) loop and is highly expressed in serum exosomes." (PMID 35986010, 2022). "In contrast, similar serum FSCN1 determinations, performed in patients diagnosed with lung cancer, laryngeal carcinoma and hepatocellular carcinoma, were correlated to tumor aggressiveness." (PMID 34737886, 2021). "In lung cancer, FSCN1 promotes cancer growth and metastasis by enhancing glycolysis and PFKFB3 expression through YAP1 activation." (PMID 35069968, 2021). "circSATB2 and FSCN1 were highly expressed while miR-326 was weakly expressed in lung cancer compared with normal adjacent tissues." (PMID 32493389, 2020). "circSATB2 positively regulated fascin homolog 1, actin-bundling protein 1 (FSCN1) expression via miR-326 in lung cancer cells." (PMID 32493389, 2020). "Analysis of the clinical characteristics of these cohorts suggested that circSATB2, miR-326, and FSCN1 expression levels were related to lung cancer lymphatic metastasis." (PMID 32493389, 2020). "Studies showed that miR-145 inhibits the migration and invasion of nasopharyngeal carcinoma and lung cancer cell lines through FSCN1 downregulation." (PMID 26657507, 2016). "High FSCN1 expression was associated with a relatively short overall survival (OS) in patients with LUAD (P = 0.0016) but not in patients with LUSC (P = 0.48), suggesting that the function of FSCN1 may vary in different lung cancer tissues." (PMID 38077434, 2023). "Our results suggest that circSATB2 could regulate fascin homolog 1, actin-bundling protein 1 (FSCN1) expression via direct binding to miR-326, further impacting the progression of lung cancer." (PMID 32493389, 2020). "Furthermore, analysis of the clinical characteristics of these lung cancer cohorts suggested that circSATB2 and FSCN1 were positively related to lung cancer lymphatic metastasis, while miR-326 was negatively related." (PMID 32493389, 2020). "Besides, miR-145 inhibits the migration and invasion of lung cancer cells via fascin homolog 1 (FSCN1) downregulation and cell growth is inhibited by miR-145, while MYC has been shown to be a direct target for miR-145." (PMID 28915579, 2017). "Moreover, the FSCN1 knockdown cell model was constructed using plasmid transfection, and the results suggested that FSCN1 promoted cell apoptosis and suppressed cell proliferation, invasion, and migration abilities of the lung cancer cell." (PMID 38077434, 2023). "The results showed PLK1, LDHA, FURIN, FSCN1, and RAB27B were up-regulated in lung cancer tissues, and MS4A1 was down-regulated in lung cancer tissues." (PMID 37604869, 2023). "FSCN1 has been reported to increase cell glycolysis to promote tumor growth and metastasis through the YAP1-PFKFB3 axis in lung cancer." (PMID 37491232, 2023). "Among the 363 up-regulated genes, 32 are prognostic markers in lung cancer, all of unfavorable prognosis, including LRP8, NUP62CL, FSCN1, PLCD3 or HMGA1." (PMID 36544755, 2022). "circSATB2 and FSCN1 were upregulated and miR-326 was downregulated in metastatic compared with non-metastatic lung cancer tissues." (PMID 32493389, 2020). "A recent study has reported two new miR-145 targets, namely, the metastasis gene FSCN1, which is regulated in nasopharyngeal carcinoma cell line invasion and metastasis and c-Myc, and TPD52, which is regulated in brain metastasis of lung cancer." (PMID 26657507, 2016).
lung cancer (continued). "Furthermore, we also found that PLK1, LDHA, FURIN, FSCN1, and RAB27B were increased in NSCLC cancerous cell lines compared with that in normal human bronchial epithelium cell line BEAS-2B, MS4A1 was down-regulated in lung cancer cells lines." (PMID 37604869, 2023). "circSATB2 and FSCN1 were upregulated while miR-326 was downregulated in lung cancer compared with normal adjacent tissues, as well as in metastatic compared with non-metastatic lung cancer tissues." (PMID 32493389, 2020).
non-small cell lung carcinoma (13 papers, 2017 to 2025). A group of at least three distinct histological types of lung cancer, including non-small cell squamous cell carcinoma, adenocarcinoma, and large cell carcinoma. "Similarly, high expression of FSCN1 has been identified in patients with increased risk for recurrence in breast and non-small-cell lung cancer." (PMID 34737886, 2021). "It promotes the development of non-small cell lung cancer (NSCLC) by upregulating fascin homolog 1 (FSCN1) and actin-bundling protein 1 via miR-326 regulation." (PMID 41299506, 2025). "Significantly elevated concentrations of serum FSCN1 have been described in head and neck cancer (HNC) patients and in non-small cell lung cancer (NSCLC) patients compared with healthy controls." (PMID 34248854, 2021).
hepatocellular carcinoma (12 papers, 2015 to 2025). A malignant tumor that arises from hepatocytes. "The aim of this study was to analyze the expression level of FSCN1 protein in liver cancer tissues and explore its diagnostic and application value in differentiating between hepatocellular carcinoma (HCC) and intrahepatic cholangiocarcinoma (ICC)." (PMID 38698008, 2024). "By specifically targeting and reducing the expression of TGF-β1, FSCN1 (Fascin Actin-Bundling Protein 1), and vimentin, EA exhibited the potential to obstruct pivotal processes closely associated with the development and progression of hepatocellular carcinoma (HCC)." (PMID 38002335, 2023). "FSCN1 plays a crucial role in doxorubicin resistance by facilitating the epithelial-mesenchymal transition (EMT) in hepatocellular carcinoma cells." (PMID 37634036, 2024). "In hepatocellular carcinoma, FSCN1 is overexpressed, and by promoting EMT, FSCN1 increases the chemoresistance capacity of hepatocellular carcinoma." (PMID 37491232, 2023).
ovarian carcinoma (11 papers, 2014 to 2023). A malignant neoplasm originating from the surface ovarian epithelium. "In vitro and in vivo data showed that the loss of FSCN1 significantly inhibited trans-mesothelial migration of the ovarian cancer cell line ES-2 and reduced the interaction between ovarian cancer cells and mesothelial cells in the mouse peritoneal cavity." (PMID 34830909, 2021). "In different cancers, including colon, pancreatic, breast, lung, esophagus, stomach, skin, and ovarian cancers, elevated expression of FSCN1 is associated with increased metastatic potential and poor prognosis, indicating its role as a candidate potential biomarker and therapeutic target." (PMID 34830909, 2021). "LncRNA CRNDE not only stimulates ovarian cancer progression by sponging miR-423-5p to upregulate FSCN1 expression, but also activates the miR-183/CCNB1 axis as an oncogene." (PMID 37934582, 2023). "A recent study examined the effect of curcumin against FSCN1 in the ovarian cancer cell line SKOV3 and found curcumin to inhibit STAT3 via the JAK/STAT3 signaling pathway." (PMID 34830909, 2021). "On the other hand, previous studies also reported overexpression of FSCN1 in epithelial ovarian cancer and indicated the interaction between cell and matrix as a vital step in the progression of malignant epithelial ovarian neoplasms." (PMID 34830909, 2021). "MiR-145 blocked epithelial-mesenchymal transition of ovarian cancer cells by targeting FSCN1, inhibited glutamine metabolism by targeting c-myc, inhibited the Warburg effect by targeting HK2, and regulated RNA methylation by targeting YTHDF2." (PMID 33419459, 2021). "Taken together, our results show that 20(S)-Rg3 blocks EMT by targeting DNMT3A/miR-145/FSCN1 pathway in ovarian cancer cells, highlighting the potentiality of 20(S)-Rg3 to be used as a therapeutic agent for ovarian cancer." (PMID 28881818, 2017). "Taken together, our data suggested that miR-145 blocked EMT by targeting FSCN1 in ovarian cancer cells." (PMID 28881818, 2017). "Here we provided the evidence that overexpression of FSCN1 was sufficient to confer EMT to ovarian cancer cells, and its aberrant elevation in ovarian cancer tissues was possibly benefited from miR-145 diminution." (PMID 28881818, 2017). "Furthermore, DAB2 promotes EMT and enhances cell migration and proliferation in ovarian cancer and urothelial carcinoma of the bladder, and FSCN1 can positively regulate EMT and extracellular matrix disassembly." (PMID 36176992, 2022). "In addition, the authors detected elevated FSCN1 expression in cell cultures derived from patients with stage IV ovarian cancer compared with cell cultures derived from stage II-III ovarian cancer patients." (PMID 34830909, 2021). "Moreover, overexpression of FSCN1 in SKOV3 (ovarian cancer cell line) triggered trans-mesothelial migration." (PMID 34830909, 2021). "Similar to ovarian cancer, studies were performed to detect FSCN1 expression in uterine cancer." (PMID 34830909, 2021). "In addition to blocking FSCN1, in curcumin-exposed ovarian cancer cells, the formation of filopodia was disrupted, and cell migration was reduced." (PMID 34830909, 2021). "miR-145 inhibits ovarian cancer cells migration and invasion by targeting FSCN1 and FLNB." (PMID 33419459, 2021). "FSCN1 is overexpressed in a variety of cancer types, including bladder and ovarian cancer." (PMID 32699531, 2020). "FSCN1 is verified as the target of miR-145 to suppress EMT in human ovarian cancer cells." (PMID 28881818, 2017).